RNU6-1258P (RNA, U6 small nuclear 1258, pseudogene)
Gene: Small nuclear RNA gene on chromosome 14 (93,437,400 to 93,437,510, reverse strand). Ensembl gene ENSG00000252720.
Homologues: Orthologues: chimpanzee U6 (99% identical), rabbit U6 (55% identical), dog U6 (51% identical), mouse Gm25768 (51% identical), dog U6 (50% identical), dog U6 (48% identical). Paralogues in human: RNU6-1309P (65% identical), RNU6-657P (65% identical), RNU6-939P (65% identical), RNU6-1091P (64% identical), RNU6-1099P (64% identical), RNU6-1130P (64% identical), RNU6-1141P (64% identical), RNU6-1164P (64% identical), RNU6-11P (64% identical), RNU6-1328P (64% identical), RNU6-204P (64% identical), RNU6-208P (64% identical), and 1287 more.